UCHL1 (ubiquitin C-terminal hydrolase L1)
Description:
Deubiquitinase that plays a role in the regulation of several processes such as maintenance of synaptic function, cardiac function, inflammatory response or osteoclastogenesis. Abrogates the ubiquitination of multiple proteins including WWTR1/TAZ, EGFR, HIF1A and beta-site amyloid precursor protein cleaving enzyme 1/BACE1. In addition, recognizes and hydrolyzes a peptide bond at the C-terminal glycine of ubiquitin to maintain a stable pool of monoubiquitin that is a key requirement for the ubiquitin-proteasome and the autophagy-lysosome pathways. Regulates amyloid precursor protein/APP processing by promoting BACE1 degradation resulting in decreased amyloid beta production. Plays a role in the immune response by regulating the ability of MHC I molecules to reach cross-presentation compartments competent for generating Ag-MHC I complexes (By similarity). Mediates the 'Lys-48'-linked deubiquitination of the transcriptional coactivator WWTR1/TAZ leading to its stabilization and inhibition of osteoclastogenesis (By similarity). Deubiquitinates and stabilizes epidermal growth factor receptor EGFR to prevent its degradation and to activate its downstream mediators (By similarity). Modulates oxidative activity in skeletal muscle by regulating key mitochondrial oxidative proteins (By similarity). Enhances the activity of hypoxia-inducible factor 1-alpha/HIF1A by abrogateing its VHL E3 ligase-mediated ubiquitination and consequently inhibiting its degradation.
Synonyms: UCH-L1; PGP9.5; UCHL-1; HEL-117; HEL-S-53; NDGOA; PARK5; PGP 9.5; PGP95; SPG79; SPG79A
Tractability: Small molecule: a structure with a bound ligand is known; a high-quality ligand is known; it has a binding pocket of medium quality; it belongs to a druggable protein family. Antibody: its Gene Ontology location is reachable by antibodies, with high confidence. PROTAC: ubiquitination databases record sites on it; its protein half-life has been measured; a small molecule that binds it is known.
Target class: Cysteine protease CA clan; Cysteine protease; Enzyme; Protease; Cysteine protease C12 family
Chemical probes: IMP-1710 (high quality), PD158481 (high quality)
Gene: Protein-coding gene on chromosome 4 (41,256,413 to 41,268,560, forward strand). Ensembl gene ENSG00000154277.
Subcellular location: Cytoplasm; Endoplasmic reticulum membrane
Subcellular location (Human Protein Atlas): Cytosol; Nucleoplasm
Pathways (Reactome):
Metabolism of proteins: UCH proteinases
Gene Ontology:
Molecular function: alpha-2A adrenergic receptor binding; cysteine-type deubiquitinase activity; cysteine-type endopeptidase activity; omega peptidase activity; protein binding; signaling receptor inhibitor activity; ubiquitin binding; ubiquitin protein ligase binding
Biological process: negative regulation of MAPK cascade; positive regulation of glycolytic process; protein deubiquitination; proteasome-mediated ubiquitin-dependent protein catabolic process; protein catabolic process; regulation of macroautophagy; ubiquitin-dependent protein catabolic process
Cellular component: cytoplasm; cytosol; nucleoplasm; plasma membrane; endoplasmic reticulum membrane
Genetic constraint (gnomAD): Loss-of-function variants: 5 observed, 30.53 expected, observed/expected ratio (o/e) 0.16, 90% interval 0.085 to 0.34. The synonymous counts are far from expectation, so gnomAD's model fits this gene poorly and the ratio says little. Missense variants: 236 observed, 272.38 expected, observed/expected ratio (o/e) 0.87, 90% interval 0.78 to 0.96. Synonymous variants: 132 observed, 102.07 expected, observed/expected ratio (o/e) 1.29, 90% interval 1.12 to 1.49.
Gene-disease validity (ClinGen):
ClinGen rates the evidence that UCHL1 causes each of these diseases.
hereditary spastic paraplegia (autosomal dominant): Definitive. Hereditary spastic paraplegias (HSP) comprise a genetically and clinically heterogeneous group of neurodegenerative disorders characterized by progressive spasticity and hyperreflexia of the lower limbs.
hereditary spastic paraplegia (autosomal recessive): Moderate.
Homologues: Orthologues: macaque UCHL1 (99% identical), pig UCHL1 (97% identical), mouse Uchl1 (96% identical), rat Uchl1 (96% identical), dog UCHL1 (90% identical), chimpanzee UCHL1 (88% identical), rabbit UCHL1 (84% identical), guinea pig UCHL1 (76% identical), tropical clawed frog uchl1 (66% identical), zebrafish uchl1 (65% identical), Drosophila melanogaster Uch (44% identical), Caenorhabditis elegans ubh-3 (33% identical), and 2 more. Paralogues in human: UCHL3 (55% identical), BAP1 (25% identical), UCHL5 (23% identical).
Diseases named in the same sentence as UCHL1 in open-access papers:
UCHL1 is named in the same sentence as 319 diseases in open-access papers, as found by Europe PMC text mining. Sharing a sentence is not in itself a finding about the gene and the disease. The quoted sentences say what the papers report.
Parkinson disease (111 papers, 2007 to 2025). A progressive degenerative disorder of the central nervous system characterized by loss of dopamine producing neurons in the substantia nigra and the presence of Lewy bodies in the substantia nigra and locus coeruleus. "Several neurodegenerative diseases, including Parkinson’s disease, Alzheimer’s disease, and amyotrophic lateral sclerosis, have been linked to UCHL1 dysfunction." (PMID 41036271, 2025). "Loss‐of‐function mutations and oxidative modifications of UCHL1 have also been linked to Parkinson's disease and Alzheimer's disease." (PMID 38087504, 2024). "UCHL1 has been implicated in sperm development, breast cancer, cardiac hypertrophy, and Parkinson’s disease, among other disorders." (PMID 38478109, 2024). "In humans, genetic Uchl1 alterations have been associated to neurological disorders, e.g., spastic paraplegia and Parkinson’s disease, mainly due to altered proteostasis via accumulation of ubiquitinated proteins and/or impaired autophagic clearance." (PMID 38538704, 2024). "Impaired UCHL1 activity has been associated with several neurodegenerative diseases including AD, Parkinson’s disease, and Amyotrophic Lateral Sclerosis." (PMID 37454217, 2023). "UCHL1 has been reported to be strongly associated with Parkinson’s disease (PD) and Alzheimer’s disease (AD) in humans." (PMID 35875077, 2022). "This analysis revealed that the genes implicated in Parkinson’s disease (Atp5a1, Ndufa7, Ndufb2, Ndufs8, Park7, Cox7a2, Cox7c, Cox6b1, Cycs, Uchl1) were upregulated in thia-exposed mice (p-value = 4.2E-3)." (PMID 34295895, 2021). "Membrane-associated farnesylation of UCHL1 was reported to promote α-synuclein accumulation, which is related to Parkinson’s disease and has an important role in the transport of Epstein-Barr virus primary oncoprotein LMP1 to the exomes." (PMID 32512887, 2020). "For instance, a dominant mutation in Uchl1, which decreases the in vitro hydrolytic activity of UCHL1, has been linked to higher risk of developing Parkinson's disease." (PMID 29590634, 2018). "Mutations in UCHL1 have been identified in Parkinson’s patients, whereas a gain-of-function mutation in the corresponding mouse gene resulted in Parkinson’s disease symptoms." (PMID 27188386, 2017). "Nevertheless, UCHL1 is highly expressed in the brain and retina, and inactivation of this protein is associated with neurodegenerative diseases such as Alzheimer and Parkinson’s disease." (PMID 28472177, 2017). "Deregulated expression and mutations in UCHL1 are associated with human diseases including cancer, Parkinson’s disease, Alzheimer disease and type 2 diabetes." (PMID 29126443, 2017). "We have previously shown that a natural lncRNA antisense to the Ubiquitin carboxyl-terminal esterase L1 (AS Uchl1), a Parkinson’s disease-associated gene, is able to increase UchL1 protein synthesis at the post-transcriptional level." (PMID 27265476, 2016). "We have recently shown that AS Uchl1, a natural lncRNA antisense to the Parkinson's disease-associated gene Ubiquitin carboxyl-terminal esterase L1 (Uchl1), is able to increase UchL1 protein synthesis at post-transcriptional level." (PMID 26029048, 2015). "UCHL1 is associated with a rare form of Parkinsonism and its accumulation is likely to play a pathological role in inclusion formation in Parkinson's diseases." (PMID 26097878, 2015). "Because rare polymorphisms in the human UCHL1 gene (also known as PARK5) have been associated with altered risk for Parkinson's disease we examined dopaminergic neuronal projections in the striatum of UCHL1 null mice." (PMID 24994982, 2014). "Genes including ATP13A2, DJ-1, GIGYF2, HTRA2, LRRK2, PARK2 (parkin), PINK1, SNCA and UCHL1 were associated with either autosomal dominant or recessive form of Parkinson's disease." (PMID 24688734, 2013). "In Network 13, we observed the UCHL1 gene, which is a neuron specific gene, previously implicated in Parkinson’s disease." (PMID 23028713, 2012).
Parkinson disease (continued). "A protective role of the p.S18Y polymorphism of the UCHL1 gene has been shown in Parkinson's disease." (PMID 21268678, 2011). "Two genes in the high confidence lists have been linked to heritable forms of Parkinson's disease (alpha-synuclein (Snca) and Uchl1)." (PMID 21253556, 2011). "Studies have documented 2 separate polymorphisms in human UCHL-1 that associate with either increased or decreased susceptibility to Parkinson's disease, although the concordance of these studies is variable." (PMID 18671875, 2008). "The putative Parkinson's disease causing allele in UCHL-1 results in a 50% decrease in enzyme catalytic activity." (PMID 18671875, 2008). "UCHL-1, a susceptibility gene for Parkinson's disease, exhibited CNS region-specific age- and CR-related changes in expression." (PMID 17988385, 2007). "Protective effects of a UCHL1 variant were observed in a mouse model of Parkinson's disease, indicating this protein may also serve as a target for Parkinson's therapies." (PMID 34335440, 2021). "UCHL1 was originally identified as a neuron-specific protein highly expressed in the nervous system, and its mutations are associated with neurodegenerative diseases, including Parkinson’s disease and Alzheimer’s disease." (PMID 31700166, 2020). "UCHL1 gene mutations are involved in Parkinson disease 5 that is characterized by a complex neurodegenerative disorder with manifestations ranging from typical Parkinson disease to dementia with Lewy bodies." (PMID 31495056, 2019). "UCHL1 is abundantly expressed in nervous system tissues, and gene variants and changes in the activity of UCHL1 have been associated with neurodegenerative disorders such as Alzheimer’s, Parkinson’s and Huntington’s diseases." (PMID 24450868, 2014). "Uchl1 is very abundant in neurons and has been associated with Parkinson and Alzheimer's disease." (PMID 23738220, 2013). "The S18Y polymorphism of the UCHL1 gene confers protection against Parkinson's disease." (PMID 20302621, 2010). "The S18Y polymorphism of the UCHL1 gene is associated with lower incidence of Parkinson's disease." (PMID 20302621, 2010). "A point mutation affecting the ligase activity of UCHL1 has been linked to Parkinson's disease, while an internal 42-amino-acid deletion in UCHL1 is responsible for murine gracile axonal dystrophy, which is characterized by axonal degeneration and formation of spheroid bodies in nerve terminals." (PMID 17244347, 2007). "Both bisphenols affected pathways such as “PARK2/PINK1/UCHL1 in Young Onset Parkinson’s Disease”, “TNF activation of NF-kB Expression Targets”, and “Androgen Receptor/FKBP5 Signaling”." (PMID 41012393, 2025). "In vitro, 1-(3,4-dihydroxybenzyl)-1,2,3,4-tetrahydroisoquinoline, an endogenous parkinsonism-inducing dopamine derivative, binds to UCHL1 specifically at Cys152." (PMID 38279302, 2024). "Interesting, CXCL5 and MARCO are both related to inflammation, while UCHL1 is a gene specific for Parkinson’s disease but also described in AD." (PMID 36012501, 2022). "For instance, Parkinson disease uses UCHL1 as a substrate and as a regulator to accelerate the degradation of UCHL1 through the autophagy system." (PMID 35546675, 2022). "The plasma levels of ubiquitin C-terminal hydrolase L1 (UCHL1) were significantly higher in late Parkinson's disease patients compared to healthy controls and the amount of UCHL1 correlated to disease severity." (PMID 34335440, 2021). "Ubiquitin C-terminal Hydrolase-1 (UCHL1) is a deubiquitinating enzyme, which plays a key role in Parkinson’s disease (PD)." (PMID 28300150, 2017). "1,2,3,4-tetrahydroisoquinoline (DHBnTIQ) is an endogenous parkinsonism-inducing dopamine derivative that binds to UCHL1 specifically at Cys152 in vitro." (PMID 28300150, 2017). "In fact, Uchl1, Otub1 and Atxn3 are involved in neurodegenerative diseases in human, namely Parkinson's disease and cerebellar ataxia, thus indicating a relevant role in neurodegeneration." (PMID 26934049, 2016).
Parkinson disease (continued). "The top three interactors returned by mouseNET (Uchl1, Dbh and Snca) are already labeled with Parkinson's disease in OMIM, indicating the ability of our system to accurately identify other disease genes given some known ones." (PMID 18818725, 2008). "Subsequent chemoproteomic evaluation with 8RK64, an alkyne-bearing derivative of 8RK59, revealed enrichment of not only UCHL1 but also protein deglycase PARK7/DJ1, an attractive target in Parkinson’s disease with a similar molecular mass that overlaps with UCHL1 by gel analysis." (PMID 37111304, 2023). "However, the function of UCHL1 was wildly reported to regulate various bioecological processes, such as Parkinson's disease, lung cancer, breast cancer and colon cancer, how UCHL1 affects the mammalian reproductive system remains an open question." (PMID 36218038, 2023). "Beyond cancer, it has been used in an attempt to target or inhibit UCHL1 in numerous disease models including for Parkinson’s disease, Alzheimer’s disease, spinal muscular atrophy (SMA), chronic liver disease, inflammatory disease, atrial fibrillation, cardiac disease and lung injury." (PMID 34497382, 2022). "There has been a suggestion of a link between UCHL1 and Parkinson’s disease, although this association has not been confirmed." (PMID 33646413, 2021). "Monoubiquitination of the residues near the active site of UCHL1 can restrict its enzymatic activity by inhibiting the binding of Ub to UCHL1, promoting the progression of neurodegenerative diseases, including Alzheimer’s and Parkinson’s disease." (PMID 34177595, 2021). "For instance, the activity of UCHL1, an abundant DUB in the brain, is negatively regulated by mono-ubiquitination and its dysfunction is implicated in several neurodegenerative diseases including Parkinson’s disease." (PMID 32512887, 2020). "For instance, the specific distribution and activity of UCHL1 in human tissues has the potential clinical significance for Parkinson’s disease (PD) and Alzheimer’s disease (AD), might be a major target of reactive oxygen species (ROS) damage." (PMID 33585209, 2020). "Previous studies have shown UCHL1 (PARK5) to co-aggregate with α-synuclein in Lewy bodies of Parkinson’s disease patients and aggregation/unfolding could be promoted by secondary modifications such as HNE." (PMID 32560738, 2020). "Both UCHL1 and UCHL1-AS are downregulated in Parkinson’s disease." (PMID 30669611, 2019). "The UCHL1 gene is known as PARK5, and its mutations are associated with Parkinson disease; indeed the I93M mutation shows severely diminished hydrolase activity and lower E3 activity, while the S18Y mutant has greater hydrolase activity but lower E3 activity than WT." (PMID 26881020, 2016). "Human UCHL1 is a neuron-restricted protein that acts as a de-ubiquitinating enzyme, ubiquitin ligase or monoubiquitin stabilizer, and its inactivation was reported in both AD and Parkinson’s disease (PD) patients." (PMID 24624135, 2014). "However, its connection to several query genes (Tbp and Mapt) and to several proteins functionally related to the query set (Mdm2, Fyn, Psen1, Apoe, Uchl1, and Dbh) in mouseNET suggests its potential role in Parkinson's disease." (PMID 18818725, 2008). "Furthermore, UCHL1 has been found to be significantly higher in the plasma of Parkinson's disease (PD) patients at moderate stages of disease, when compared with early-stage counterparts and healthy controls, reflecting a possible correlation with PD pathology." (PMID 38716888, 2024). "UCHL1 (also known as PGP 9.5) is the most studied member of the UCH-class of cysteine protease DUBs and is associated with multiple types of cancers including lung, colorectal, pancreatic, and breast cancers as well as neurodegenerative diseases such as Parkinson's and Alzheimer's." (PMID 25605410, 2015).
Parkinson disease (continued). "Decreased abundance of UCHL1 has been reported in CSF from patients with synucleinopathies, and in tissue from FTD, people with Alzheimer's disease and Parkinson's disease." (PMID 39548852, 2025). "As a protein biomarkers for central nervous system damage, UCHL1 has been detected in diverse brain injuries including ischemic/hemorrhagic stroke, TBI, Parkinson’s disease, cardiac arrest, and seizures." (PMID 34504487, 2021). "From the Parkinson’s disease KEGG enrichment result, five of differently expressed piRNAs-aligned genes (NDUFA4, CALM3, UCHL1, CALM2, and HSPA5) in the prefrontal cortex (15 genes) overlapped with differently expressed piRNAs-aligned genes in the amygdala (16 genes)." (PMID 35269612, 2022). "At least 19 genetic loci for Parkinsonism have been identified to date, ten of which are autosomal dominant genes: SNCA (PARK1/PARK4), PARK3, UCHL1 (PARK5), LRRK2 (PARK8), GIGYF2 (PARK11), HTRA2 (PARK13), VPS35 (PARK17), EIF4G1 (PARK18), TMEM230 (PARK21), and CHCHD2 (PARK22)." (PMID 34356877, 2021). "UCHL1, a member of the UCH subfamily of DUBs, is highly expressed in neurons, and is involved in several neurodegenerative diseases, including Alzheimer’s and Parkinson’s disease." (PMID 34177595, 2021). "However, proteomic analysis of brain mitochondria from mice with MPTP-induced Parkinsonism did not reveal UCHL1 among oxidatively modified proteins." (PMID 38279302, 2024). "Although 6RK73 showed more potent inhibition against UCHL1 and better cellular engagement than LDN-57444, it showed limited cellular selectivity with a range of off-targets, particularly against PARK7, a redox-responsive chaperone protein involved in Parkinson’s disease." (PMID 34497382, 2022). "Nevertheless, UCHL1 and FBXO7 interact with ParkinIP proteins, and therefore the RelatedPD subnetwork consists of a single connected component when ATP13A2, which is responsible for Kufor-Rakeb syndrome, a form of parkinsonism with dementia and juvenile disease onset, is excluded." (PMID 24244333, 2013). "In Parkinson's disease and other neurodegenerative conditions the dysfunction seen in CNS neurons similarly affects those in the periphery, and it is therefore reasonable to assume that the absence of UCHL1 would also affect neuronal populations outside the CNS." (PMID 24994982, 2014).